RAF1 (Raf-1 proto-oncogene, serine/threonine kinase)
Diseases named in the same sentence as RAF1 in open-access papers (continued):
Sharing a sentence is not in itself a finding about the gene and the disease.
tumor (continued). "This analysis demonstrated that expression levels of MMP1 and MMP12 were increased in patients with residual tumors post-treatment, whereas RAF1 expression was higher in patients who were tumor-free post-treatment." (PMID 40362553, 2025). "The SOCA library screening results showed that multiple combinations were associated with Raf1 knockout, and Raf1‐NTC emerged as a significant outlier in the linear regression analysis of the cell pool versus tumour." (PMID 39073026, 2024). "It is a multi-target kinase inhibitor that blocks tumor cell proliferation by inhibiting the activity of RAF-1, B-Raf, and other kinases in the Ras/Raf/MEK/ERK signaling pathways." (PMID 38650929, 2024). "Aberrant expression of RAF1 was found in many types of cancers and is related to tumor angiogenesis." (PMID 39076089, 2024). "Sorafenib is a multikinase inhibitor that suppresses tumor cell proliferation by inhibiting B-Raf, Raf-1, and kinase activity in the Ras/Raf/MEK/ERK signaling pathways." (PMID 38270798, 2024). "The abundance of the Raf1‐Pkm2 gene pair was significantly reduced within the tumour, suggesting progressive selection pressure as the cells pool to form the primary tumour." (PMID 39073026, 2024). "By suppressing the activity of VGFR-2, VGFR-3, and RAF-1, it effectively hampers tumor cell proliferation through direct blockade of the RAF/MEK/ERK-mediated signaling pathway." (PMID 39850566, 2024). "We transplanted DKO, SKO and NTC cells of Raf1‐Pkm2 and Raf1‐Top2α into nu/nu mice (n = 5‒6) to measure tumour growth." (PMID 39073026, 2024). "As a consequence, our data demonstrated that the tumor suppressive effect of miR-605-3p in OS was achieved mainly by RAF1." (PMID 39076089, 2024). "Because of Raf1’s role in angiogenesis, tumors have a reduced ability to develop resistance to siRNA targeting Raf-1 of tumor vessels." (PMID 39683699, 2024). "Our immediate interest in the carrier is targeting Raf-1, a key mediator of tumor growth and angiogenesis." (PMID 39683699, 2024). "Since the tumor microenvironment comprises various types of cells, like malignant cells, tumor-infiltrating immune cells, and endothelial cells, we performed single-cell RNA sequencing to identify which cell type is responsible for RAF1 upregulation." (PMID 38655096, 2024). "The results showed that Raf1_Top2α and Raf1‐Pkm2 significantly inhibited tumour growth compared with the corresponding single‐knockout group and WT group." (PMID 39073026, 2024). "PEPB1, also known as the RAF kinase inhibitor protein (RKIP), is a tumor suppressor that inhibits the RAF1-MAPK and NFkappaB signaling pathways and the G protein-coupled receptor (GPCR) kinase, resulting in the suppression of tumor progression and metastasis." (PMID 36765875, 2023). "Of the 77 patients with RAF1 aberrations, 25 patients (32.5%) had RAF1 copy number variations (CNVs) in their tumor specimens." (PMID 38137485, 2023). "Comprehensive genomic profiling (CGP) of 3,633 pediatric cancer patients revealed RAF1 fusions in seven distinct pediatric tumor types." (PMID 38111008, 2023). "It functions by inhibiting the growth of tumor cells and the formation of blood vessels through targeting various serine/threonine and tyrosine kinases such as RAF1, BRAF, VEGFR 1, 2, 3, PDGFR, KIT, FLT3, FGFR1, and RET." (PMID 37299411, 2023). "Of the 77 patients with RAF1 aberrations, 10 patients (13.0%) had RAF1 fusions in their tumor specimens." (PMID 38137485, 2023). "The up-regulation of PPID protein induced by oncogenic Ras through the Raf-1/MEK/ERK pathway has a decisive role in tumor progression." (PMID 37714937, 2023). "On the other hand, ARID1A expression loss triggers a variety of pathways related to tumor progression and metastasis, including the ErbB pathway, VEGF pathway, HIF-1 pathway and RAF1 pathway, to participate in metastasis." (PMID 36869329, 2023).
tumor (continued). "The inhibition of VEGFR2 and VEGFR3 also contributes to the remission of tumor metastasis through antiangiogenic and antiproliferative mechanisms, while the inhibition of RAF-1, RET, and KIT pathways leads to reduced cell proliferation and increased apoptosis." (PMID 38068319, 2023). "Meanwhile, RAF-1 overexpression is also considered as an independent marker of early tumor recurrence and poor prognosis." (PMID 37180166, 2023). "Since the discovery of oncogenic RAF1, there has been a concerted effort to develop therapeutic inhibitors to attenuate its aberrant activity in tumor cells." (PMID 38111008, 2023). "Overall, RAF1 aberrations were observed in the tumors of 77 patients (2.0%) among a total of 3895 patients whose tumor specimens were subjected to NGS." (PMID 38137485, 2023). "Multitargeted tyrosine kinase inhibitors (TKIs), such as sorafenib, can suppress tumor cell proliferation by inhibiting Raf-1, B-Raf, and kinase activity in the Ras/Raf/MEK/ERK signaling pathway." (PMID 37296859, 2023). "Through bioinformatic analyses and dual-luciferase reporter assays, we showed that circXPO1 directly bound to miR-7-5p, which acted as a tumor suppressor through the negative regulation of RAF1." (PMID 36980172, 2023). "In vivo experiments further demonstrated that down-regulation of RAF1 inhibited tumor growth and lymphatic metastasis." (PMID 35668458, 2022). "Regorafenib, a multi-kinase inhibitor, inhibits several numbers of protein kinases implicated in tumour growth (KIT, RET, RAF-1, and BRAF p38 MAP kinase), metastasis (PDGFR- and FGFR1), and tumour angiogenesis (VEGFR-1, -2, and -3)." (PMID 36614133, 2022). "Taken together, RKIP exerts cardiotoxic effects by multiple pathways (i) as a tumour metastasis suppressor and inhibitor of the RAF1-MAPK axis and (ii) as a GRK2 inhibitor." (PMID 35203304, 2022). "Sorafenib suppresses tumor cell proliferation by inhibiting serine/threonine kinase Raf-1 in the RAF/MEK/ERK signaling pathway." (PMID 34976171, 2022). "To further confirm the expression of RAF1 in clinical tumor tissue specimens, we assessed RAF1 mRNA and protein levels by qRT-PCR and WB assay." (PMID 35668458, 2022). "As a multitarget kinase inhibitor, sorafenib blocks tumor cell proliferation by inhibiting the activity of Raf-1, B-Raf, and kinases in the Ras/Raf/MEK/ERK-signaling pathway." (PMID 35216404, 2022). "In conclusion, reduced expression of RAF1 can significantly inhibit the proliferation, migration and invasion of tumor cells, and promote the apoptosis of tumor cells." (PMID 35668458, 2022). "In mechanistic murine studies on RAS-driven tumors, Braf and Raf1 have been discovered to be either crucial or completely dispensable in the initiation of tumor development dependent on disease entity." (PMID 35965494, 2022). "Meanwhile, sorafenib suppresses tumor angiogenesis and proliferation by inhibiting multikinases such as the serine/threonine kinase family (e.g., Raf-1, PI3K/Akt, ERK1/2, and STAT3) and the receptor tyrosine kinase family (e.g., FGFR, VEGFR, and PDGFR)." (PMID 35770048, 2022). "The major functions of RKIP as a tumour suppressor are mediated by its main activity as an inhibitor of the proto-oncogenic and pro-survival RAF1-MAPK pathway." (PMID 35203304, 2022). "Expression of RAF1 is lower in HCC than in peripheral non-tumor tissues, and the magnitude of this difference negatively correlates with tumor grade." (PMID 35836300, 2022). "Consistent with this, treatment with sorafenib, a RAF/ERK inhibitor, significantly decreased tumor weight and expression of RAF1 and ZEB1, a downstream effector of the RAF/ERK pathway, in HHUA-SP-derived tumors but not non-SP-derived tumors." (PMID 35659728, 2022). "ERBB2 and RAF1 were altered in 37% and 45% of G3pT1 tumours, respectively, but only in 5% and 10% of G1pTa tumours, respectively." (PMID 35655252, 2022).
tumor (continued). "Unfortunately, the function and mechanism of RAF1 in tumor progression and lymphatic metastasis of head and neck squamous cell carcinoma has not been explored." (PMID 35668458, 2022). "The cardiotoxic effects of the tumour suppressor RKIP can be attributed to inhibition of the pro-survival RAF1-MAPK pathway." (PMID 35203304, 2022). "Ablation of Raf1 induced significant tumor regression, including a complete disappearance in 10% of tumors, likely as a consequence of increased rates of apoptosis." (PMID 35965494, 2022). "Taken together, RKIP is a kinase inhibitor and metastasis suppressor, which inhibits tumour cell invasiveness by inhibition of RAF1 and interference with other tumour-promoting pathways." (PMID 35203304, 2022). "A second strain expressing an independent RAF1 kinase dead isoform (RAF1K375M) displayed a somewhat limited tumor burden." (PMID 34951114, 2022). "In this study, in vivo and in vitro experiments proved that knockdown LAGE1 can also inhibit tumor development and lymphatic metastasis, which is consistent with the inhibitory effect of knockdown RAF1." (PMID 35668458, 2022). "On the contrary, in the lv-RAF1-OE group, tumor growth was faster than in the control group, and the incidence of lymphatic metastasis was higher." (PMID 35668458, 2022). "RKIP is an endogenous tumour metastasis suppressor with detrimental cardiac effects due to RAF1-MAPK pathway inhibition and its specific mode of GRK2 inhibition." (PMID 35203304, 2022). "In general, in vivo results indicated that increased RAF1 expression promoted both tumor growth and lymphatic metastasis." (PMID 35668458, 2022). "As a kinase inhibitor of multiple targets, it is capable of blocking tumor cell multiplication via restraining the activation of Raf-1, B-RAF and kinases in Ras/Raf/MEK/ERK pathway." (PMID 34367979, 2021). "Sorafenib suppresses tumor cell proliferation by inhibiting Raf-1, B-Raf, and kinase activity in the Ras/Raf/MEK/ERK signaling pathways." (PMID 34683920, 2021). "Expression of KRASG12V in murine lungs resulted in the development of tumours, which was significantly reduced when RAF1 was knocked out as well." (PMID 33920182, 2021). "MiR-16 overexpression reduced cell proliferation in vitro and tumor growth in mice by targeting directly the IGF1R with subsequent inhibition of the Raf1- Mitogen-Activated Protein Kinase Kinase 1/2 (MEK1/2)-ERK1/2 pathway." (PMID 34484116, 2021). "Sorafenib is an orally administered multikinase inhibitor that decreases tumor cell proliferation by blocking Raf-1, wild-type B-Raf and the mitogen-activated protein kinase (MAPK) extracellular signaling-regulated kinase (ERK) signaling pathway." (PMID 32575795, 2020). "A sorafenib-targeted gene, RAF1 expression, was increased in tumor tissues especially in the sorafenib-resistant group." (PMID 32190741, 2020). "In the literature, RAF1 inhibition was shown to induce autophagy and tumor regression in a conditional mouse model for RAF1-induced lung tumorigenesis." (PMID 33066037, 2020). "This suggests a dual role of StarD13; as 1- a tumor suppressor which attenuates RhoA (hence Raf-1/MEK/ERK proliferation and survival pathway) as well as 2- an invasion suppressor, which inhibits Cdc42." (PMID 32900380, 2020). "RAF1 has been reported to play a carcinogenic role in human cancers and is related to tumor angiogenesis." (PMID 30610161, 2019). "The present study showed that Raf1 was a direct target of miR-485-5p to function as a tumor promoter." (PMID 31870440, 2019). "Analysis of tumour tissues by Western blot confirmed reduced Raf‐1 expression and elevated p70S6K protein levels within the tumours." (PMID 31541523, 2019). "Raf1 has been studied to act as a tumor promoter in many cancers, such as osteosarcoma, gastric cancer, non-small cell lung cancer." (PMID 31870440, 2019). "RAF1 has been reported to have oncogenic effect in human cancers and its relationship with tumor angiogenesis has also been revealed." (PMID 30610161, 2019).
tumor (continued). "In this study, we identified a non‐canonical Raf‐1/p70S6K signalling pathway in NSCLC where Raf‐1 targets p70S6K as its downstream effector to regulate NSCLC tumour growth via sustaining proliferation, inhibiting apoptosis and promoting cell cycle progression." (PMID 31541523, 2019). "Tumours were measured and weighed, and Raf‐1 and p70S6K expression, cell proliferation and apoptosis were examined in tumour tissues by Western blot, Ki‐67 staining and TUNEL staining, respectively." (PMID 31541523, 2019). "Raf-1-RBD pull-down experiments for KRAS activity were also carried out using total cell lysates isolated from tumor tissues." (PMID 30971271, 2019). "Combination of LErafAON with DOX or paclitaxel (PTX) led to significantly enhanced antitumor activity in all the tumor types, compared with LErafAON-alone or chemotherapeutic agent-alone treated groups, through inhibition of Raf-1 expression in tumor tissue." (PMID 30347840, 2018). "Sorafenib suppresses tumour proliferation by inhibiting the mitogen-activated protein kinase (MAPK) family members Raf-1 and B-Raf." (PMID 29246127, 2017). "It has been shown that sorafenib decreases tumor cell proliferation via raf-1 (as well as wild-type braf and v599e braf) inhibition and that it effectively blocks the raf/mek/erk signaling pathway in cancer cells." (PMID 29270287, 2017). "This plasmid-based approach with cRGD liposomal carriers of dominant-negative mutants of Raf-1 not only inhibited tumor xenografts, but also resulted in their regression." (PMID 29218233, 2017). "These tumor cells have initialmutations as driver gene mutations, whereas HCC has few mutations in the Raf1 kinase gene." (PMID 26769852, 2016). "In Δp/np mice, liver:body weight ratios and tumour-occupied areas were only slightly increased; however, RAF1 ablation increased tumour multiplicity and malignancy (7 out of 10 Δp/np animals developed HCC, compared with 3 out of 8 F/F mice)." (PMID 28000790, 2016). "Sorafenib, a multikinase inhibitor, is thought to exert its antitumoral effects through the inhibition both angiogenesis and tumor cell proliferation by receptor tyrosine kinases, such as the serine-threonine kinases Raf-1, VEGFR1-3, and PDGFR-β." (PMID 26981887, 2016). "We analysed RAF1 expression in paired tumour and non-tumour tissue of each of 31 human HCC specimens." (PMID 28000790, 2016). "Taken together, these results highlighted that suppression of both MKK-7/c-Jun and Raf-1/Fra-1 activities was involved in the tumor-growth inhibitory effects exerted by SAHA in vivo, in agreement with the in vitro data." (PMID 26734995, 2016). "The multi-kinase inhibitor sorafenib, originally developed to block Raf-1 in tumor cells with aberrant Ras signaling, also targets B-Raf, although its efficacy in B-Raf driven melanoma has been disappointing." (PMID 27034005, 2016). "More importantly, a tremendous increase in tumour mass was observed in HCC xenografts in nude mice when RAF1 was knocked down in vivo by adding doxycycline to the drinking water." (PMID 28000790, 2016). "The changes in HER2, p-HER2, Raf-1, Akt, and p-Akt protein levels were then checked in the excised tumor tissues." (PMID 24927996, 2014). "Higher levels of phospho-ERK1/2, phospho-MEK1/2 and phosphor-Raf-1 were consistently observed in RASAL2 knockdown tumor samples." (PMID 25216515, 2014). "It acts by blocking the activities of the serine-threnoine kinases Raf-1 and B-Raf, and the receptor tyrosine kinases of the vascular endothelial growth factor receptors, consequently inhibiting tumor-cell proliferation and tumor angiogenesis." (PMID 25460347, 2014).
tumor (continued). "RRD-251 was developed as an antineoplastic drug that abolishes the phosphorylation of pRb by specifically disrupting the physical interaction between Raf-1 and pRb, and this has been shown to increase the apoptosis of tumor cells both in vitro and in vivo." (PMID 24391814, 2013). "RRD-251 is a small molecule disruptor of the Rb–Raf-1 interaction that significantly inhibits angiogenesis and tumor growth both in vitro and in vivo in a pRb-dependent manner." (PMID 24391814, 2013). "Disruption of the pRb–Raf-1 interaction induces apoptosis in malignant tumor cells and inhibits cell proliferation." (PMID 24391814, 2013). "Knockdown of KDR, PKCα, PLCγ and Raf1 by siRNA significantly attenuated tumour inhibitory effects of brucine." (PMID 23905676, 2013). "Sorafenib, an orally active multikinase inhibitor with effects on tumor-cell proliferation and tumor angiogenesis, was initially identified as a Raf kinase inhibitor, by inhibiting the serine-threonine kinase Raf-1 and B-Raf." (PMID 22721173, 2012). "Sorafenib is a multi-kinase inhibitor that targets several receptor tyrosine kinases including, VEGFR-1, -2 and -3 and PDGFR-β, and serine threonine kinases including, Raf-1 and B-Raf, all shown to be involved in neovascularization and tumor progression." (PMID 23113927, 2012). "In HNPC tumours, Raf-1 correlated with the inactive form, pRaf (Ser259), before relapse (P=0.0041, r2=0.1201)." (PMID 21559022, 2011). "Tumour regression is characterised by massive, runaway differentiation, which was a surprise in view of the well-established role of Raf-1 in proliferation and of its essential antiapoptotic function in other cell types." (PMID 21081934, 2011). "In particular, we will focus on the recently established role of Raf-1 as the decisive element that, by restraining keratinocyte differentiation, allows the development and maintenance of Ras-driven tumours." (PMID 21081934, 2011). "Sorafenib has demonstrated ability to inhibit RAF-1 and tumor cell line proliferation as well as tumor growth in multiple human tumor xenograft models." (PMID 22654559, 2011). "TLN-4601 treatment resulted in a decrease of Raf-1 protein levels in xenograft tumor tissues (p = 0.02), which is similar to the effects observed in vitro." (PMID 21044336, 2010). "Preclinical studies of this drug have shown inhibition of tumour growth, more than 50% inhibition of raf-1 expression in tumour xenografts and increased sensitization of tumour cells to radiation and to chemotherapeutic agents." (PMID 19787090, 2008). "BAY 43-9006 is a potent inhibitor of Raf-1 (the Ras/Raf signalling pathway being an important mediator of tumour cell proliferation and angiogenesis), VEGFR and PDGFR TKIs." (PMID 15928655, 2005). "Notably, Raf-1 reduction likely will lead to decreased PD-L1 expression on tumor and tumor endothelial cell surfaces." (PMID 39683699, 2024). "Additionally, the Raf-1 signaling pathway is a critical signal node during ubiquitination, which determines the biological processes of tumor cells." (PMID 38376606, 2024). "In clinical samples, tumour microarray experiments confirmed a positive correlation between the expression levels of Raf1 and Pkm2 in tumour tissue, suggesting that Raf1‐Pkm2 may serve as a synergistic therapeutic target for HCC development." (PMID 39073026, 2024). "Among the genes, ACTG1, CAT, and RAF1 were upregulated in tumor tissues relative to normal tissues." (PMID 38806963, 2024). "The expression levels of Raf1‐Pkm2 in tumour and adjacent tissues were statistically significant." (PMID 39073026, 2024). "Furthermore, restoration of RAF1 obviously reversed the tumor suppressive effect of miR-605-3p in OS." (PMID 39076089, 2024). "We also found mutation only in the tumor tissue in the genes DICER, ESR1, KIT, PDGFRA, and RAF1." (PMID 38565739, 2024). "In addition, we determined the variation in the abundance of DKO, SKO and NTC‐NTC of the Raf1‐Pkm2 gene pair in cell pools and tumour screens." (PMID 39073026, 2024).